CFTR (CF transmembrane conductance regulator)
Diseases named in the same sentence as CFTR in open-access papers (continued):
Sharing a sentence is not in itself a finding about the gene and the disease.
COVID-19 (continued). "This would place CFTR-modifying therapeutics in a prime position to alter the course and severity of the COVID-19 pathology." (PMID 33250777, 2020). "Although there is a reasonable basis to propose that CFTR dysfunction occurs in COVID-19, several caveats apply." (PMID 33250777, 2020). "Given the dire mortality and morbidity statistics for COVID-19, we believe that there is sufficient evidence to support initiating proof of concept clinical trials addressing the potential benefit of CFTR therapeutics in patients with COVID-19." (PMID 33250777, 2020). "Based on descriptions of more severe COVID-19 in adult CF carriers, who have only one copy of wildtype CFTR, we suggest that this model-based conclusion may be consistent with otherwise normal patient-based experience." (PMID 39043712, 2024). "We therefore hypothesized that inflammation in the COVID-19 airway might similarly be due to inhibition of CFTR signaling by SARS-CoV-2 spike protein, and therefore activation of both NFκB and ENaC signaling." (PMID 39043712, 2024). "Besides, there is good evidence that effective CFTR modulation can improve mucus clearance from the airways representing a protective factor in preventing COVID-19 viral infections." (PMID 37957647, 2023). "Thus, host genetic and phenotypic factors were shown involved in determining COVID-19 presentation and progression, including CFTR channel and ACE-2 expression." (PMID 37957647, 2023). "It has also been demonstrated in vitro that the recovery of CFTR expression and function by CFTR modulators treatment is associated with a sudden increase in viral replication, in contrast to clinical observation reporting a less severe outcome of COVID-19 in pwCF in case of CFTR modulators therapy." (PMID 37250046, 2023). "Moreover, the application of the new machine learning post-Mendelian model to a large international cohort of COVID-19 patients extracted the CFTR gene as an important factor involved in the modulation of COVID-19 outcomes." (PMID 36552859, 2022). "Further studies are needed to dissect the interaction between CFTR and SARS-CoV-2, including the understanding of how the different SARS-CoV-2 variants may affect the clinical presentation of COVID-19 in individuals with loss-of-function CFTR genotypes." (PMID 36552859, 2022). "Detangling the role of CFTR in COVID-19 pathogenesis would for sure help to better understand such deadly disease, considering also that a previous GWAS study has described an intronic variant in the CFTR gene to be highly represented in patients with pneumonia." (PMID 34203982, 2021). "Such a finding reveals that COVID-19 mortality is determined by time-dependent factors and that CFTR-related early events like cytokine storm may be responsible for early death." (PMID 34203982, 2021). "In conclusion, while more studies should be performed to understand the role of CFTR in COVID-19 pathogenesis, in our opinion, the presented results may have relevant and immediate clinical implications." (PMID 34203982, 2021). "This reinforces the interest in studying the specific role of CFTR in the pathogenesis of COVID-19." (PMID 34950129, 2021). "Ablation of tight junction protein claudin 1 and down-regulation of apical sodium-dependent bile acid transporter (ASBT) and cystic fibrosis transmembrane conductance regulator (CFTR) might be the contributing factors towards liver injury in COVID-19." (PMID 33498861, 2021). "First and foremost, deficient CFTR activity has not been established in COVID-19 and the net effect of a CFTR deficiency in a complex response involving multiple cytokines and cell types remains to be characterized." (PMID 33250777, 2020). "In this perspective, we propose that CFTR therapeutics, which are safe and generally well-tolerated, may provide benefit to COVID-19 patients." (PMID 33250777, 2020).
COVID-19 (continued). "Indeed, tumor necrosis factor (TNF), a key cytokine driving COVID-19 pathogenesis, downregulates lung CFTR protein expression, providing a strong rationale that acquired CFTR dysfunction arises in the context of COVID-19 infection." (PMID 33250777, 2020). "It is tempting, therefore, to speculate that, in addition to its direct effects on lung function, CFTR therapeutics may have a “value-added effect” of dampening exaggerated immune responses that damage the lungs of COVID-19 patients." (PMID 33250777, 2020). "From this perspective, it may be that people with CF, who have appropriate modifier genes, may have a genetic propensity to survive without CFTR, and thus to also have lower risk of severe COVID-19." (PMID 39043712, 2024). "Furthermore, this work suggests that CFTR and possibly other chloride channels could be taken into consideration as molecular targets for the development of alternative anti-COVID-19 therapies." (PMID 36627352, 2023). "The drug of the second generation of CFTR modulators—elexacaftor/tezacaftor/ivacaftor (VX-445 + VX-661 + VX-770)—prescribed after an additional examination on intestinal organoids, showed a clinical effect of 16%, despite COVID-19, lung damage, and the presence of chronic aspergillosis." (PMID 36286063, 2022). "Further encouraged by the parallel between COVID-19 and CF in terms of activation of both ENaC and TNFα/NFκB signaling, we have hypothesized that inflammation in the COVID-19 airway might be due to inhibition of CFTR signaling in normal lung epithelial cells by the SARS-CoV-2 spike protein." (PMID 39043712, 2024). "However, some reports have shown that SARS-CoV-2 infection unexpectedly caused mild clinical manifestations in pwCF, suggesting that CFTR expression and function, or pharmacological treatments such as CFTR modulators might be involved and, in some way, influence the pathophysiology of COVID-19." (PMID 37957647, 2023). "On the other hand, in individuals with CF a modulation of CFTR with increased opening frequency, and thus a restoration of the channel function with modulating agents, may result in an improvement of mucociliary clearance, lung microbiota, acting as defence mechanisms against severe COVID-19." (PMID 37957647, 2023). "Our study provides evidence that CFTR expression/function is involved in the regulation of SARS-CoV-2 replication, thus providing novel insights into the role of CFTR in SARS-CoV-2 infection and the development of therapeutic strategies for COVID-19." (PMID 35456026, 2022). "Thus, it is intriguing to propose that CFTR therapeutics could represent a safe means of improving neurological symptoms, reducing the incidence and severity of strokes, and minimizing long-term cognitive impact in COVID-19 patients." (PMID 33250777, 2020). "According to a recent publication, CFTR may additionally affect the severity of SARS-CoV-2 infection and COVID-19 ailments in CF patients." (PMID 38694803, 2024). "In addition to targeting the primary lung pathology, CFTR therapeutics may possess value-added effects: their anti-inflammatory properties may dampen exaggerated immune cell responses and promote cerebrovascular dilation; the latter aspect may offer some protection against COVID-19 related stroke." (PMID 33250777, 2020). "Thus, it is conceivable that in CF carriers the concomitant downregulation of CFTR and ACE2—having both events a proinflammatory effect—may lead to a more severe COVID-19 clinical presentation." (PMID 34203982, 2021). "To date, the protective factor against COVID-19 in patients with CF, and the role and correlation of CFTR and ACE-2, and of CFTR modulating agents, is not fully elucidated." (PMID 37957647, 2023).
chronic rhinosinusitis (24 papers, 2009 to 2026). Chronic form of sinusitis. "The researchers concluded that this finding had therapeutic implications for chronic rhinosinusitis recommending clinical studies ‘targeting topical administration to the sinuses, including individuals with relative deficiency in CFTR activity’." (PMID 41070403, 2025). "The present study demonstrated that extensive genotyping is essential and productive in patients with atypical presentation such as a single CFTR gene mutation and severe chronic rhinosinusitis." (PMID 31788264, 2019). "Meanwhile, some individuals with isolated chronic rhinosinusitis have signs and symptoms suggestive of CFTR dysfunction that do not satisfy CF diagnostic criteria, prompting clinicians to refer to this affliction as CFTR‐related disorder." (PMID 34557648, 2021). "We propose that thorough clinical and functional assessment in severe chronic rhinosinusitis is valuable to discover rare mutations which could be treated by CFTR correctors to postpone pulmonary infection." (PMID 31788264, 2019). "Furthermore, genetic studies have suggested that the CFTR mutation responsible for CF might in itself be a predisposing factor for sinus disease, by demonstrating an increased occurrence of CFTR mutations in the general population with chronic rhinosinusitis." (PMID 22919396, 2012). "It is characterized by the triad of bronchiectasis, chronic rhinosinusitis, and obstructive azoospermia despite normal CFTR function." (PMID 41009940, 2025). "Severe chronic rhinosinusitis in children should alert clinicians and extensive CFTR genotyping should be performed." (PMID 31788264, 2019). "Augmenting fluid and electrolyte secretion represents a means of improving mucus clearance in individuals affected by acute or chronic rhinosinusitis, specifically in the setting of WT CFTR." (PMID 25117505, 2014). "Similarly, CFTR mutations have been reported in increased frequency among patients with non-CF chronic rhinosinusitis." (PMID 24517344, 2014). "Inducible deficiencies in transepithelial Cl− transport via CF transmembrane conductance regulator (CFTR) has been theorized to be a driving process in recalcitrant chronic rhinosinusitis (CRS) in patients without CF." (PMID 39865444, 2025).
pancreatic cancer (24 papers, 2011 to 2025). "The relative risk of pancreatic cancer in patients with a CFTR gene mutation is 5.3 (95% CI: 2.4–10.1)." (PMID 39200847, 2024). "In conclusion, the association between CF, CFTR, and pancreatic cancer involves intricate molecular mechanisms." (PMID 37686519, 2023). "While the incidence of CP in patients with CF is relatively low (<2%), there are several studies that have found an association between CFTR mutations and both CP and pancreatic cancer." (PMID 35743652, 2022). "Several studies have also found that germline variants in the CFTR gene are linked to both pancreatitis and an increase in pancreatic cancer risk, including familial pancreatic cancer." (PMID 35743652, 2022). "Inherited heterozygous CFTR mutations have been associated with an increased risk of pancreatic cancer among both younger and older patients." (PMID 32326161, 2020). "For example, CFTR downregulation in pancreatic cancer cells leads to increased levels of tumour-linked mucin MUC4, altering the growth and behaviour of pancreatic adenocarcinomas." (PMID 32365523, 2020). "Different cohort studies have investigated how different variants of CFTR affect the risk of pancreatic cancer." (PMID 33178018, 2020). "The prevalence of CFTR mutations in pancreatic cancer is estimated range between 5 and 8%." (PMID 35720978, 2022). "A separate study proposed that interactions between CFTR polymorphisms with environmental factors might be responsible for the development of pancreatic cancer." (PMID 35743652, 2022). "Patients with chronic pancreatitis have a 26-fold higher risk for developing pancreatic cancer compared to the general population, suggesting that CFTR mutation could be considered as a new risk factor for developing PDAC." (PMID 33178018, 2020). "Some attention has been given to the connection between pancreatic cancer risk and CFTR deficiency." (PMID 33178018, 2020). "Whereas there is no disagreement concerning the adequacy of a non-smoking advice other reports find a modest increased risk for carriers of disease-relevant CFTR mutations (OR:1.4; 95%CI: 1.04–1.89) and are more reluctant concerning the role of CFTR mutations as risk factors of pancreatic cancer." (PMID 24600409, 2014). "The authors claim that the clinical features were not influenced by the presence of a gene mutation except for an earlier age at onset and a higher incidence of pancreatic cancer, especially in patients with a CFTR mutation (four cancer patients had CFTR mutations, one a PRSS1 mutation)." (PMID 24600409, 2014). "CFTR dysfunction, pancreatic duct obstruction, chronic inflammation, altered bile flow, CFTR-related genetic factors, impaired nutrient absorption, and microbiota dysbiosis collectively contribute to the increased risk of pancreatic cancer in individuals with CF." (PMID 37686519, 2023). "In case of hereditary pancreatitis caused by mutations in the PRSS1, CFTR, SPINK1 genes, pancreatectomy becomes advisable, including for prevention of pancreatic cancer." (PMID 39896151, 2024). "A follow up study by the McWilliams group again found a significant increase in pancreatic cancer in carriers of the CFTR gene (5.3% versus 3.8%) along with a younger average onset (62 versus 67 years)." (PMID 35720978, 2022). "Silencing of CFTR was found to enhance the expression of MUC4 in pancreatic cancer cells." (PMID 35743652, 2022). "Although PRSS1 and CPA1 variants have been linked to pancreatic cancer risk, to date variants in other chronic pancreatitis susceptibility genes such as SPINK1 and CFTR have not been consistently found to be risk factors for pancreatic cancer." (PMID 28881607, 2017). "Observation of somatic VUS is important since some, though not all (e.g., CFTR), pancreatic cancer predispositions genes, could come from families whose members may develop other type of tumors." (PMID 33747920, 2021).
pancreatic cancer (continued). "Furthermore, studies also indicate that patients who are CFTR mutant carriers develop pancreatic cancer in a younger age, compared to patients carrying a wildtype form of CFTR, and patients carrying a germline mutation to some degree have an increased risk of developing PDAC." (PMID 33178018, 2020). "As MUC4 is a protein involved in tumor migration and metastasis, the negative regulation by CFTR indicates a protective role and a tumor suppressing function by inhibiting MUC4 and hence pancreatic cancer progression." (PMID 33178018, 2020). "Although we found HAVCR2 and CFTR cited together in a 2019 paper related to pancreatic cancer, their ratio does not seem biologically meaningful." (PMID 33572894, 2021).
chronic lung disease (23 papers, 2009 to 2025). According to the definitions of the American and British Thoracic Societies, including pulmonary functional tests, X-rays, and CT scans for items such as fibrosis, bronchiectasis, bullae, emphysema, nodular or lymphomatous abnormalities. "The co-segregation of p.Cys1400Ter with c.489+3A>G, even in the absence of additional pathogenic variants on the other CFTR allele, may be associated with chronic lung disease or potential CFTR-related disorders (CFTR-RD) in older individuals." (PMID 40301948, 2025). "Since the IL-8 inflammatory response is a hallmark of CF chronic lung disease, and CFTR mutations in AEC may lead to dysregulated inflammatory signalling, we sought to test the effect of SAF/PAF co-stimulation in a CF-relevant AEC cell lines." (PMID 26360879, 2015). "Despite the mitigation of remodeling phenotypes, chronic lung diseases will certainly still require other treatments such as antibiotics, anti-inflammatories, and/or CFTR modulators (e.g., E/T/I) in the case of CF." (PMID 37039381, 2023). "In contrast, other groups believe that CFTR dysfunction in CF results in exaggerated NFκB signaling that leads to chronic lung disease." (PMID 19247502, 2009). "An enhanced understanding of CFTR-lipid interactions should not only provide a more accurate model of CF and other chronic lung diseases, but may aid in the identification of new drug targets, or lead to modulation of current therapies." (PMID 32313074, 2020). "Hence, CFTR-autophagy dysfunction in chronic lung diseases such as CF and COPD leads to P. aeruginosa exacerbations." (PMID 32847034, 2020). "Moreover, the rescue of mutant CFTR to the PM corrects the autophagy-mediated immune dysfunction, controlling chronic lung disease pathogenesis." (PMID 32847034, 2020). "It is conceivable that decreased expression of some transcripts during chronic lung disease may expose the CFTR mRNA to the destabilizing effect of miR-143, miR-145 or other miRNAs." (PMID 31590401, 2019). "Our data increase understanding of the role of TGF-β1 in CF and other forms of chronic lung disease and may help to develop future strategies to achieve the full benefit of the transformative CFTR therapies in CF patients homozygous for F508del." (PMID 31590401, 2019). "In summary, our data increase understanding of the role of TGF-β1 in CF and other forms of chronic lung disease and may help to develop future strategies to achieve the full benefit of the transformative CFTR therapies in patients homozygous for F508del." (PMID 31590401, 2019). "Whether such modifications increase sensitivity of CFTR mRNA to TGF-β1 during chronic lung disease will also have to be addressed by future studies." (PMID 31590401, 2019). "Although it is clear that the fundamental cause of CF is the lack of functional CFTR protein, the mechanisms leading to chronic lung disease associated with infection need further study." (PMID 26469863, 2015). "However, CFTR modulator therapies are also generating new insights which will continue to advance our understanding of chronic P. aeruginosa respiratory infections, both in CF and other chronic lung diseases." (PMID 39015565, 2024). "Here, we show that chronic lung disease, including CF, creates a permissive environment for TGF-β1-miRNA cross-talk, leading to selective recruitment of validated CFTR inhibitors to RISC and decay of CFTR mRNA." (PMID 31590401, 2019). "Next, we examined how TGF-β1 affects the expression of miR-145 and CFTR mRNA in HBE cells from lungs homozygous for F508del, COPD or IPF (other disease), or control group from lungs without known chronic lung disease." (PMID 31590401, 2019). "Moreover, our recent data suggests that selective proteasome inhibition also helps in controlling chronic inflammation that will be required for treating the patients with chronic lung disease, as rescuing misfolded CFTR may not be sufficient for favorable therapeutic outcome." (PMID 20868490, 2010).